Y_RNA (Y RNA )
Gene: Miscellaneous RNA gene on chromosome 4 (61,906,313 to 61,906,408, forward strand). Ensembl gene ENSG00000202169.
Homologues: Orthologues: chimpanzee Y_RNA (100% identical), dog Y_RNA (78% identical), guinea pig Y_RNA (74% identical), guinea pig Y_RNA (68% identical). Paralogues in human: RNY4P7 (84% identical), RNY4 (83% identical), Y_RNA (83% identical), RNY4P10 (81% identical), RNY4P14 (81% identical), RNY4P3 (81% identical), RNY4P9 (81% identical), Y_RNA (81% identical), RNY4P19 (80% identical), RNY4P23 (80% identical), RNY4P25 (80% identical), RNY4P6 (80% identical), and 88 more.